RPS3 (ribosomal protein S3)
Diseases named in the same sentence as RPS3 in open-access papers (continued):
Sharing a sentence is not in itself a finding about the gene and the disease.
melanoma (5 papers, 2015 to 2024). A malignant, usually aggressive tumor composed of atypical, neoplastic melanocytes. "We evaluated the association of RPS3 expression with the melanoma patient survival and clinical outcome." (PMID 26336993, 2015). "Furthermore, we showed that RPS3 was highly expressed in melanoma cell lines and melanoma tumor tissues, and overexpression of RPS3 was associated with the poor prognosis of melanoma patients." (PMID 26336993, 2015). "However, the precise physiological function of RPS3 and its underlying mechanism involved in melanoma tumorgenesis remains unclear." (PMID 26336993, 2015). "Prior studies have revealed that RPS3 regulates melanoma cell proliferation and apoptosis primarily by modulating Ca2+ signaling and MiCU1-dependent mitochondrial pathways." (PMID 38911376, 2024). "Treatment of mBRAF melanoma cells with combination mBRAFi/MEKi led to a decrease in fucosylated RPS3 as assessed by PLA and UEAI lectin PD." (PMID 34070332, 2021). "Interaction of total RPS3 with HNRNPU showed a decrease in the cytoplasmic fraction of NRAS mutant melanoma cells treated with MEKi and in BRAF mutant cells treated with combination mBRAFi/MEKi as assessed by PLA analysis." (PMID 34070332, 2021). "However, as a majority of our in vitro studies have been performed in melanoma cell lines, it is also possible that the aberrant expression of splice variants of fucosyltransferases that are no longer restricted in localization to within the ER–Golgi network mediate RPS3 fucosylation." (PMID 34070332, 2021). "UEAI PD followed by RPS3 immunoblot (IB) suggested that RPS3 is fucosylated in a number of melanoma cell lines as well as in normal mouse tissue homogenates." (PMID 34070332, 2021). "RPS3 is increased in melanoma cell lines relative to primary human epidermal melanocytes and is also increased in drug-resistant isogenic cell lines relative to drug-sensitive parental lines." (PMID 34070332, 2021). "Immunofluorescent staining analysis of a melanoma tumor microarray (TMA) revealed that total RPS3 protein levels increase with stage in melanoma patient samples." (PMID 34070332, 2021). "Incubation of 7 days, as in the 3D culture assays, was performed on two malignant cancer cell lines: HT1080 fibrosarcoma cell line, and WM-115 human melanoma cell line after knock-down of endogenous rpS3 by si-RNAs (human si-rpS3/777 and si-rpS3/796)." (PMID 27384988, 2016). "We first examined the expression of RPS3 at protein levels in five human melanoma cell lines (A375, A431, WM35, MeWo, SK-MEL-28), one immortalized normal human cell SK and two normal cell lines (fibroblast, Knot) by Western blot analysis." (PMID 26336993, 2015). "We also found that knockdown of RPS3 significantly inhibited tumor growth in a melanoma xenograft mouse model." (PMID 26336993, 2015). "In this study, we demonstrated that ribosomal protein S3 (RPS3) was a potential target involved in melanoma growth." (PMID 26336993, 2015). "In summary, we discovered and identified ribosomal protein S3 (RPS3) was a potential molecular target for melanoma." (PMID 26336993, 2015). "Knockdown of RPS3 by siRNA-3 or siRNA-4 effectively inhibited cell clonogenicity, resulting in a marked decrease in colony formation ratio in melanoma A375 cells." (PMID 26336993, 2015). "To identify the possible mechanisms of RPS3 in melanoma cells, we next detected the effects of RPS3 knockdown on mitochondrial transition pore status and Ca2+ dependent signaling." (PMID 26336993, 2015). "Consistent with the results from Western blot analysis, the high levels of RPS3 proteins were detected in melanoma tumor tissues." (PMID 26336993, 2015). "We also investigated the role of RPS3 in regulating tumor growth in melanoma cell line and xenograft mouse model and evaluated its clinical significance in melanoma patients." (PMID 26336993, 2015).
melanoma (continued). "The median survival time of the melanoma patients with low expression of RPS3 was 24.5 months, whereas the median survival time of the melanoma patients with high expression of RPS3 was 10 months." (PMID 26336993, 2015). "To confirm the roles of RPS3 in the regulation of melanoma growth and survival, we analyzed the effect of RPS3 on tumorigenicity in vivo using a xenograft mouse model." (PMID 26336993, 2015). "We also analyzed the relationship of hazards ratio and survival time with RPS3 protein expression in melanoma patients." (PMID 26336993, 2015). "We next investigated the role of RPS3 in the regulation of melanoma growth by plotting the growth curves." (PMID 26336993, 2015). "The RPS3 protein levels were up-regulated in all five melanoma cell lines and the immortalized cell (SK) by comparison with the RPS3 expression in two normal cell line (fibroblast, Knot)." (PMID 26336993, 2015). "Instead of stimulating melanoma cells proliferation, the RPS3 knockdown-mediated flooding of Ca2+ into mitochondrial induced apoptosis." (PMID 26336993, 2015). "We also performed the colony formation experiment to confirm the effect of RPS3 on melanoma cell growth." (PMID 26336993, 2015). "We further confirmed the role of RPS3 in the regulation of mitochondrial calcium ions (Ca2+) in melanoma cells." (PMID 26336993, 2015). "We found that HNRNPU does localize to the cytoplasmic fraction by both subcellular fractionation and immunofluorescence analysis, and its steady state protein levels are also increased in melanoma cell lines relative to primary cells, consistent with those of RPS3." (PMID 34070332, 2021). "In this study, we identified RPS3 as a novel melanoma target by siRNA knockdown." (PMID 26336993, 2015). "Knockdown of RPS3 by siRNA suppressed cell growth and induced apoptosis in melanoma cells." (PMID 26336993, 2015). "Furthermore, we showed that RPS3 was highly expressed in various melanoma cell lines and melanoma tumor tissues and the overexpression of RPS3 was associated with the poor prognosis of patients." (PMID 26336993, 2015). "Since the growth inhibitory effect was observed in the siRPS3-transfected melanoma cells, we next analyzed whether RPS3 mediated the accumulation of the apoptotic sub-G1 cell population in A375 cells by flow cytometry." (PMID 26336993, 2015). "In addition, we also analyzed the effect of RPS3 on the mitochondrial signaling in melanoma cells to elucidate the possible molecular mechanism of RPS3." (PMID 26336993, 2015). "To further confirm the high expression of RPS3 in melanoma and to investigate the clinicopathological significance of RPS3 expression, we also analyzed the expression of RPS3 in tumor tissues from 60 cases of patients with melanoma by immunohistochemical staining assay." (PMID 26336993, 2015). "Our results therefore demonstrate that RPS3 regulates melanoma growth through the modulation of the Cyto C/Ca2+/MICU1 dependent mitochondrial signaling and suggest that RPS3 is a potential therapeutic target for melanoma treatment." (PMID 26336993, 2015). "To gain insight into how fucosylation of RPS3 may impact protein function, we tested by lectin-mediated PLA and Western blot whether fucosylation level responds to stimulus in melanoma cells." (PMID 34070332, 2021). "The RPS3-positive staining was observed in melanoma cells of tumor tissues, but the staining was negative in the adjacent non-tumor tissue samples surrounding tumors." (PMID 26336993, 2015). "Our results therefore demonstrated that RPS3 regulated melanoma growth through the modulation of the Ca2+/MICU1 dependent mitochondrial signaling and suggest that RPS3 is a potential therapeutic target for melanoma treatment." (PMID 26336993, 2015).
oral squamous cell carcinoma (5 papers, 2019 to 2023). "RPS3 has been demonstrated to be involved in DDP resistance of oral squamous cell carcinoma." (PMID 33644057, 2021).
cervical carcinoma (4 papers, 2021 to 2025). A carcinoma arising from either the exocervical squamous epithelium or the endocervical glandular epithelium. "For instance, in cervical cancers, how FLCs interact with proteins like RPL7, RPS3, H1-5, and H1-6, and the exact process of FLCs promoting sarcoma proliferation, are not yet fully understood." (PMID 40806736, 2025). "By observing the difference in the expression levels of key genes in the different types of cervical cancer and normal tissues, we found that most genes, such as RPS27A, RPS3, and EEF1B2, were significantly expressed in cervical cancer." (PMID 34796111, 2021).
COVID-19 (4 papers, 2021 to 2024). A disease caused by infection with severe acute respiratory syndrome coronavirus 2. "This study also did not investigate the functional roles of the identified hub gene containing RPS3, which limits the understanding of its potential importance in COVID-19 pathogenesis." (PMID 38370514, 2024). "This study identified three compounds—baicalein, vadadustat, and estetrol—with promising properties, such as binding affinity and residual interaction with RPS3, for COVID-19 treatment." (PMID 38370514, 2024). "The current study and findings from these two earlier studies suggest that RPS3 could be a potential therapeutic target for COVID-19." (PMID 38370514, 2024). "There was a positive correlation between the COVID-19-related protein RPS3 and IGF2R." (PMID 35720320, 2022). "Although no subsequent literature has demonstrated COVID-19 vaccination-induced differential expression of RPL10, RPS3, and RPS4X in CD4+ T cells, these genes are still considered potent features." (PMID 36936955, 2023).
glioma (3 papers, 2020 to 2023). A benign or malignant brain and spinal cord tumor that arises from glial cells (astrocytes, oligodendrocytes, ependymal cells). "Interestingly, glioma cancer cells have reduced levels of LTV1 and produce ribosomes lacking RPS3, RPS10, and RACK1." (PMID 33334055, 2020).
hepatocellular carcinoma (3 papers, 2017 to 2023). A malignant tumor that arises from hepatocytes. "As an RNA-binding protein (RBP), RPS3 has been reported as a promising drug target for hepatocellular carcinoma." (PMID 37091868, 2023). "To date, eL36 (rpL36) plays a role in cisplatin resistance in human carcinoma cells, the radiosensitivity in NSCLC (non-small cell lung cancer) cells is regulated by uS3 (rpS3), and eL24 (rpL24) may have effects on drug resistance mechanisms in hepatocellular carcinoma HepG2 cells." (PMID 28273808, 2017).
liver cancer (3 papers, 2020 to 2025). An epithelial or non-epithelial malignant neoplasm that arises from the liver. "It has been reported that human ribosomal protein S3 (RPS3) regulates the expression of silent information regulator 1 (SIRT1) after transcription to promote liver cancer." (PMID 33228611, 2020). "The inhibition of RPS3/SIRT1 pathway by 5-formylfuran-2-yl methyl 4-hydroxy-2-methylenebutanoate (FMHM) represses HCC progression suggesting that RPS3/SIRT1 could serve as a potential therapeutic target in liver cancer." (PMID 34873618, 2021).
non-small cell lung carcinoma (3 papers, 2017 to 2021). A group of at least three distinct histological types of lung cancer, including non-small cell squamous cell carcinoma, adenocarcinoma, and large cell carcinoma. "Phospho-RPS3 translocates into the nucleus and upregulates prosurvival gene expression via association with NF-κB in non-small cell lung cancer cells." (PMID 31620119, 2019).
adenoid cystic carcinoma (2 papers, 2022 to 2025). A malignant tumor arising from the epithelial cells. "Further supporting a role for RPS3 in tumour cell invasion and migration, siRNA-mediated reduction in RPS3 expression in BLB/C nude mice resulted in reduced adenoid cystic carcinoma migration, invasion, and cisplatin resistance." (PMID 40940922, 2025). "A small study of 73 patients with adenoid cystic carcinoma treated with cisplatin found that 37 patients had high tumour expression of RPS3 and this correlated with a higher incidence of tumour metastasis and poorer prognosis compared to patients with low tumour RPS3 expression." (PMID 40940922, 2025).
eumycotic mycetoma (2 papers, 2021 to 2022). A chronic granulomatous inflammation involving the deep dermis and the subcutaneous tissues. "Diseases associated with RPS3 include Eumycotic Mycetoma and Schopf-Schulz-Passarge Syndrome." (PMID 35401659, 2022).
Parkinson (2 papers, 2021 to 2023). "The understanding of damaged mtDNA/Rps3-mediated neurodegeneration holds promises in elucidating the mechanisms underlying the propagation of Parkinson’s pathology throughout the brain and its progression to dementia." (PMID 37779111, 2023). "RPS3 protected cells in the substantia nigra against MPTP-induced oxidative stress in a mouse model of Parkinson’s disease and RPL24 had time and dose-dependent effects on HepG-2 cell growth inhibition." (PMID 34798813, 2021).
psoriasis (2 papers, 2021 to 2025). An autoimmune condition characterized by red, well-delineated plaques with silvery scales that are usually on the extensor surfaces and scalp. "We identified PSMA6, a reported genetic risk factor for the development of psoriasis and IBD52,53, PSMA7 (proteasome 20S subunit alpha), a biomarker of IBD54, and RPS3 (ribosome small 40S subunit) as potential LZTR1-interacting proteins, while only PSMA7 and RPS3 were validated through co-IP." (PMID 41162356, 2025).
Salmonella Infections (2 papers, 2018 to 2025). Infections with bacteria of the genus SALMONELLA. "The results showed that after RPS3 knockdown, the production of ROS in macrophages induced by S. Tm decreased, and the reduction in the number of mitochondria caused by Salmonella infection was inhibited, suggesting that RPS3 may play an important role in the defense against S. Tm infection." (PMID 41181117, 2025). "To clarify the function of RPS3 in arginine-enhanced host defense against S. Tm infection, we conducted an intersection analysis of the potential binding sites of RPS3, arginine metabolism, and Salmonella infection-related proteins." (PMID 41181117, 2025).
anaphylaxis (1 paper, 2020). An acute hypersensitivity reaction that occurs from exposure to an allergen. "In this experiment, after the broilers were fed with Bacillus cereus PAS38, the RPS3 expression in thymus and bursa of fabricius was down-regulated in the treatment group, which might be related to the reduction of anaphylaxis." (PMID 32609751, 2020).
colitis (1 paper, 2020). Inflammation of the colon. "Thus, our findings provided a novel mechanism underlying LXN modulates colitis via HECTD1/Rps3/NF-κB pathway and significant implications for the development of novel strategies for the treatment of colitis by targeting LXN." (PMID 32555320, 2020). "Our findings highlight a correlation between LXN and colitis via HECTD1/Rps3/IκBα pathway." (PMID 32555320, 2020).
cyst (1 paper, 2023). A sac-like closed membranous structure that may be empty or contain fluid or amorphous material. "However, in the RpS3-knockdown cyst, one axoneme was linked with two identical mitochondrial derivatives, both containing the accumulated paracrystalline structure similar to major mitochondrial derivatives, implying that the identities of the mitochondrial derivatives were totally disrupted." (PMID 36831240, 2023).
developmental delay (1 paper, 2026). "Previous analyses of RpS3 allelic series demonstrated that severity of bristle shortening and developmental delay is proportional to the reduction of RpS3 mRNA." (PMID 41492826, 2026).
diabetic nephropathy (1 paper, 2023). "Interestingly, RPS3 was described to be associated with diabetic nephropathy, while RPS3A was also reported to have an increased expression in membranous nephropathic kidneys." (PMID 36769128, 2023).
fibrosarcoma (1 paper, 2023). A malignant mesenchymal fibroblastic neoplasm affecting the soft tissue and bone. "RPS3 is misexpressed in multiple cancers, and overexpression of RPS3 reduces invasiveness of fibrosarcoma cells in vitro." (PMID 38628976, 2023).
fungal infection (1 paper, 2020). "After fungal infection, RPS3, RPS18, and RPL13a expressed stably in T. castaneum." (PMID 33085726, 2020).
Infertility (1 paper, 2023). "It will be of great importance to investigate whether RpS3 and/or other ribosomal proteins are directly correlated with human infertility and reproductive diseases." (PMID 36831240, 2023).
Insulin resistance (1 paper, 2025). Increased resistance towards insulin, that is, diminished effectiveness of insulin in reducing blood glucose levels. "JAK1 mediates cytokine-driven inflammation and contributes to insulin resistance in adipose tissue, while RPS3 links translational control with NF-κB activation, promoting oxidative stress in β-cells." (PMID 40909129, 2025). "Hub genes such as GNB1, JAK1, and RPS3 dominated the T2DM network layer, suggesting critical roles in inflammatory signaling, insulin resistance, and translational control under metabolic stress." (PMID 40909129, 2025).
lymph node metastasis (1 paper, 2022). "In this study, we found that high RPS3 expression in 73 ACC patient samples was associated with both lymph node metastasis, lung metastasis, and poor prognosis." (PMID 35847905, 2022).
male infertility (1 paper, 2023). The inability of the male to effect fertilization of an ovum after a specified period of unprotected intercourse. "Accordingly, this diminished sperm production in the RpS3-depleted testes caused male infertility." (PMID 36831240, 2023). "Knocking down RpS3 in testes resulted in a significant reduction in the number of mature sperm and thus male infertility of these flies." (PMID 36831240, 2023).
pancreatic cancer (1 paper, 2023). "RPL10 ufmylation was clearly observed in pancreatic cancer cells, whereas another ribosomal protein, RPS3, was unable to be modified by UFM1." (PMID 37280198, 2023).
pancreatic ductal adenocarcinoma (1 paper, 2023). An infiltrating adenocarcinoma that arises from the epithelial cells of the pancreas. "From the analysis, we finally conclude that the ribosomal protein RPS3 is the crucial biomarker involved in the AMG 510 resistance in the KRAS G12C-mutant MIA-PaCa2 cell pancreatic ductal adenocarcinoma cells." (PMID 37396909, 2023). "Furthermore, the enrichment and survival analysis revealed that the small unit ribosomal protein (RP) RPS3 is the crucial biomarker of the AMG 510 resistance in KRAS G12C-mutant MIA-PaCa2 cell pancreatic ductal adenocarcinoma cells." (PMID 37396909, 2023).
pulmonary hypertension (1 paper, 2022). Increased pressure within the pulmonary circulation due to lung or heart disorder. "To further investigate the relationships among the SRP-DGs and risk of SSc-PH, we constructed a nomogram model using seven SRP-DGs (RPL32, RPS12, RPS14, RPS23, RPS3, RPS7, and SRP9) to predict the risk of pulmonary hypertension complications in patients with SSc." (PMID 36518216, 2022).
type 2 diabetes mellitus (1 paper, 2024). A type of diabetes mellitus that is characterized by insulin resistance or desensitization and increased blood glucose levels. "RPS3 is enriched in ribosome, tyrosine metabolism, glycine serine and threonine metabolism, terpenoid backbone biosynthesis, and type II diabetes mellitus." (PMID 39044840, 2024).